CD59 (CD59 molecule (CD59 blood group))
Diseases named in the same sentence as CD59 in open-access papers (continued):
Sharing a sentence is not in itself a finding about the gene and the disease.
pancreatic cancer (8 papers, 2019 to 2025). "Our study demonstrated that CD59 was overexpressed in pancreatic cancer tissues and that a high expression level was associated with a high histological grade and a worse prognosis." (PMID 31685825, 2019). "Pancreatic cancer-educated macrophages upregulate CD59 expression on pancreatic cancer cell lines through STAT3 phosphorylation via the IL-6R/STAT3 signaling pathway and protect them from complement-dependent cytotoxicity." (PMID 40370471, 2025). "To gain further insight into the importance of IL-6 in macrophages as a key upstream factor driving CD59 up-regulation in pancreatic cancer cells, we neutralized IL-6 from the supernatants of the coculture system via a commercially available blocking antibody." (PMID 31685825, 2019). "After reducing CD59 expression in pancreatic cancer cells, the survival rate of cells decreased in the presence of the complement system." (PMID 31685825, 2019). "A tissue microarray of pancreatic cancer patients was used to evaluate the interrelationship of CD59 and TAMs and their survival impacts were analyzed." (PMID 31685825, 2019). "Our data revealed that the infiltration of TAMs and the expression of CD59 of pancreatic cancer were paralleled, and higher infiltration of TAMs and higher expression of CD59 predicted worse survival of pancreatic cancer patients." (PMID 31685825, 2019). "In summary, crosstalk between macrophages and pancreatic cancer cells through the upregulation of CD59 in an IL-6R/STAT3 manner protects pancreatic cancer from CDC." (PMID 31685825, 2019). "SiSTAT3 pancreatic cancer cells cocultured with THP-1 macrophages expressed lower amounts of CD59 than the siNC group." (PMID 31685825, 2019). "Here, we suggest that pancreatic cancer-educated macrophages induce the upregulation of CD59 in an IL-6R/STAT3-dependent manner in pancreatic cancer cells." (PMID 31685825, 2019). "To dissect the function of CD59 in pancreatic cancer cells against CDC, we used siRNAs to inhibit CD59 expression in AsPC-1 and BxPC-3, which was detected by western blot and FCM." (PMID 31685825, 2019). "We also demonstrated that IL-6 derived from pancreatic cancer-educated macrophages played vital roles in regulating the expression of CD59 in pancreatic cancer." (PMID 31685825, 2019). "In this study, the interactions and mechanisms of TAMs, CD59 and pancreatic cancer were studied, to uncover new immunotherapeutic targets for pancreatic cancer." (PMID 31685825, 2019). "We also observed that CD59 expression was positively correlated with CD163+ M2 type macrophage infiltration in pancreatic cancer tissues." (PMID 31685825, 2019). "CD59 expression correlated with TAM infiltration in pancreatic cancer tissues." (PMID 40370471, 2025). "CD59 has been reported to be highly expressed in patients with pancreatic cancer, and Pancreatic cancer-educated macrophages could up-regulate CD59 to protect cancer cells from CDC through the IL-6R/STAT3 signaling pathway." (PMID 35237592, 2022). "CD59 has also been reported to be overexpressed in several other cancers, including breast, esophageal and pancreatic cancer, and that its expression may facilitate tumor cell escape from complement surveillance." (PMID 36612172, 2022). "The overexpression of CD59 in pancreatic cancer has major consequences on the tumor microenvironment and was previously shown to be required for stem cell evasion of complement surveillance, a biological mechanism for eliminating cancer stem cells in epithelial cancer." (PMID 33613843, 2021). "In a coculture system, THP-1 cells were used as a model to study the function of TAMs and the roles of pancreatic cancer-educated macrophages in regulating the expression of CD59 in pancreatic cancer cells were demonstrated by real-time PCR, western blot and immunofluorescence staining." (PMID 31685825, 2019).
pancreatic cancer (continued). "In this study, we showed that the expression levels of CD59 in clinical specimens were positively correlated with a worse prognosis for pancreatic cancer patients and that CD59 expression was positively correlated with TAM infiltration in pancreatic cancer tissues." (PMID 31685825, 2019). "Then, the pancreatic cancer cells were incubated with various concentrations of IL-6 (0, 0.01, 1, 10 and 100 nM), and the CD59 expression and phosphorylation levels of STAT3 in cancer cells were significantly elevated to levels comparable to those in cells stimulated with THP-1 macrophages." (PMID 31685825, 2019). "To evaluate the effects of TAMs on CD59 expression in cancer cells, we examined the expression levels of CD59 protein in 7 human pancreatic cancer cell lines (BxPC-3, MiaPaCa-2, T3M4, PANC-1, AsPC-1, Su86.86, and CFPAC-1) and selected AsPC-1 as the high expression group." (PMID 31685825, 2019). "We hypothesized that IL-6, secreted by TAMs, might induce the upregulation of CD59 in pancreatic cancer cells via STAT3 activation." (PMID 31685825, 2019). "In the in vitro experiments, we found that pancreatic cancer cells were able to induce monocytes to differentiate into M2-type macrophages which could upregulate CD59 expression in cancer cells and protect cells from CDC." (PMID 31685825, 2019). "Pancreatic cancer-educated macrophages could protect cancer cells from CDC by up-regulating CD59 via the IL-6R/STAT3 signaling pathway." (PMID 31685825, 2019). "In summary, these results revealed a novel interaction between TAMs and CD59 expression in pancreatic cancer cells, and demonstrated that pancreatic cancer-educated macrophages could protect pancreatic cancer cells from CDC by regulating CD59." (PMID 31685825, 2019). "CD59 expression in pancreatic cancer tissues was much higher than that in the surrounding tissues." (PMID 31685825, 2019). "Additionally, pancreatic cancer-educated macrophages could protect cancer cells from complement-mediated cytotoxicity by up-regulating CD59 in an IL6/STAT3-dependent manner." (PMID 39518137, 2024). "Therefore, pancreatic cancer-educated macrophages could upregulate CD59 expression on cancer cells and protect cancer cells from CDC in an in vitro experiment." (PMID 31685825, 2019). "Therefore, overexpression of CD59 may be a biomarker indicating worse survival for pancreatic cancer patients." (PMID 31685825, 2019). "In this study, we observed that pancreatic cancer cells could induce macrophages to exhibit a tumor-promoting phenotype, and then the tumor-promoting macrophages induced CD59 expression in cancer cells by IL-6 secretion and by inducing IL-6R expression in cancer cells." (PMID 31685825, 2019). "The interactions between CD59, TAMs and pancreatic cancer remain largely unknown." (PMID 31685825, 2019). "CD59 expression levels as H-scores for pancreatic cancer tissues and adjacent nontumor tissues were different." (PMID 31685825, 2019). "Neutralizing IL-6 within the coculture system led to a reduction in the ability of macrophages to upregulate CD59 expression in pancreatic cancer cells, but the result was not so remarkable." (PMID 31685825, 2019). "The H-score of CD59 was significantly higher in pancreatic cancer tissues than that in nontumor tissues (p = 0.027, Mann-Whitney U test)." (PMID 31685825, 2019). "The role of CD59 in the progression and prognosis of pancreatic cancer has not yet been reported." (PMID 31685825, 2019). "However, the role of CD59 in the prognosis of pancreatic cancer has not been reported." (PMID 31685825, 2019).
colon cancer (7 papers, 2016 to 2024). "Several studies have shown successful usage of neutralizing CD55 or CD59 antibodies in colon cancer or NSCLC, but these were investigated in cell lines or in mouse xenograft models." (PMID 33362763, 2020). "Calgranulin B showed a positive correlation with stromal inflammatory cells surrounding colon cancer cells, and up-regulated CD59 has been linked to differentiation and TNM staging of colon cancer." (PMID 28036279, 2017). "Therefore, calgranulin B, CD59, and their interactions may be useful for molecular staging diagnoses and colon cancer therapies." (PMID 28036279, 2017). "The candidate proteins included caveolae-associated integral membrane protein, flotillin-1 (FLOT1); transport cargo-associated protein, dynein intermediate chain 1 (DYNC1); and CD59 glycoprotein (CD59), which may give a clue specific internalization of calgranulin B into colon cancer cells." (PMID 28036279, 2017). "It has been shown that expression levels of membrane-bound complement regulatory proteins (mCRPs), including CD46, CD55 and CD59, are considerably higher in colon cancer tissues than in normal neighboring normal colon tissues." (PMID 36612172, 2022). "Furthermore, an analysis based on TNM staging showed that the expression of CD55 and CD59 is higher in stage III and stage IV colon cancers than in stage I and stage II tumors." (PMID 36612172, 2022). "While CD46 was found to have no clinical relevance, levels of CD55 and CD59, other complement inhibitor membrane cofactor proteins, were positively correlated with the differentiation and tumor stage in colon cancers." (PMID 27203670, 2016). "Although no complement regulator polymorphisms for risk of colon cancer have been identified, CD46, CD55, and CD59 were all upregulated in colon cancer compared to adjacent healthy tissue, with CD55 and CD59 expression correlating with tumor stage and differentiation level." (PMID 33362763, 2020).
gastric cancer (7 papers, 2017 to 2024). A primary or metastatic malignant neoplasm involving the stomach. "The associations between CD59 and immune suppressive cells such as T-regulatory cells, myeloid derived suppressor cells, and macrophage create an immune suppressive environment in cervical, brain, head and neck, and stomach cancers." (PMID 39518137, 2024). "For example, flotillin-1 (FLOT1), DYNC1, and CD59 were overexpressed in colon, breast, and gastric cancer cell lines compared to normal cell lines." (PMID 28036279, 2017). "Additionally, the HPA database indicates that cancers like cervical, GBM, head and neck, melanoma, pancreatic, renal, and stomach cancers exhibit elevated CD59 expression, which significantly affects their prognosis." (PMID 39518137, 2024). "For instance, negative regulators of complement (such as CD46, CD55, and CD59) have been found to be highly expressed in gastric cancers, which could potentially explain why T+P therapies failed to offer a significant clinical benefit in the JACOB Phase III trials of gastric HER2+ cancers." (PMID 35167491, 2022). "Finally, we found that the imbalance of 11 immune regulatory factors could predict the overall survival time of gastric cancer, including EZH2, NRP1, CD59, OsBPL1aBCL11B, BASP1, HNMT, CXCR4, ASGR2, ANXA5, CDH2." (PMID 34322132, 2021).
age-related macular degeneration (6 papers, 2011 to 2025). Age-related loss of vision in the central portion of the retina (macula), secondary to retinal degeneration. "Age-Related Macular Degeneration (AMD): The complement regulatory protein CD59 reduces membrane attack complex formation, considered one of the causes of AMD, by 62%." (PMID 29326851, 2017).
autoimmune hemolytic anemia (6 papers, 2011 to 2025). Autoimmune hemolytic anemia (AIHA) is an autoimmune disorder in which various types of auto-antibodies are directed against red blood cells causing their survival to be shortened and resulting in hemolytic anemia. "Deficient expression of CD55 and CD59 has recently been reported in patients with autoimmune hemolytic anemia, autoimmune thrombocytopenia, or SLE." (PMID 22081908, 2011). "However, decreased complement regulatory components on lymphocytes and erythrocytes, including CD55 and CD59, have been shown to be associated with lymphopenia and autoimmune hemolytic anemia (AHIA)." (PMID 24592327, 2014).
B-cell lymphoma (6 papers, 2019 to 2024). "Our data reveal for the first time that susceptibility to RTX-mediated CDC in B-cell lymphoma is synergistically influenced by choice of therapeutic antibody isotype, CD20/CD59 expression ratio and tumor density." (PMID 35725455, 2022). "One explanation for this is likely the combination of CD20 with a low CD59 expression, as blocking CD59 on CD20+ B-cell lymphoma cells with a high CD59 expression, rendered them sensitive to RTX-mediated CDC when cultured in 2D." (PMID 35725455, 2022). "Collectively, these results indicate that a high CD20/CD59 expression ratio in B-cell lymphoma facilitates anti-tumor immunity by RTX." (PMID 35725455, 2022). "In line with our findings, clinical studies of B-cell lymphoma patients, treated with rituximab-cyclophosphamide, adriamycin, vincristine, and prednisone (R-CHOP), showed that high CD59 expression in tumors was associated with poor overall survival compared to patients with lower CD59 expression." (PMID 35725455, 2022). "The effect of RTX-IgG2 was further validated on Raji B-cell lymphoma cells, which express lower levels of CD20, CD47, and CD59 compared to Granta-519 cells." (PMID 39712032, 2024). "In this study we have identified several features that affect RTX-mediated CDC in B-cell lymphoma; CD20 antigen density, CD59 expression level, tumor structure, and choice of mAb isotype." (PMID 35725455, 2022). "Here we show for the first time that tumor CD20/CD59 expression ratio, tumor architecture and choice of isotype synergistically influence RTX-mediated CDC activity in B-cell lymphoma." (PMID 35725455, 2022). "The results demonstrate that CDC outcome in CD20+ B-cell lymphoma is synergistically influenced by choice of RTX isotype, antigen density, tumor structure, and degree of CD59 expression." (PMID 35725455, 2022). "Different RTX isotypes, IgG1, IgG3, IgA1 and IgA2 were evaluated and administered on four human CD20+ B-cell lymphoma cell lines, displaying diverse expression of CD20 and complement-regulatory protein CD59." (PMID 35725455, 2022). "Together, these results suggest that CD59 upregulation is mainly controlled by NF-κB and CREB in the acquired and intrinsic rituximab-resistant B cell lymphoma." (PMID 34956875, 2021). "While the KSHV-negative B-cell lymphoma cell line, BJAB, expressed CD55 and CD59, both the KSHV-infected PEL cell lines, BCBL-1 and BCP-1, did not express CD55 or CD59." (PMID 32260199, 2020). "Summary of percentage increase in phagocytosis of CD20+ B-cell lymphoma cells (Granta-519) induced by tumor-specific mAb (anti-CD20 RTX, anti-CD59, or anti-PD-L1) in combination with RTX-IgG2 or anti-CD47 mAb (where applicable) in comparison with single use of tumor-specific mAb." (PMID 39712032, 2024).
COVID-19 (6 papers, 2022 to 2024). A disease caused by infection with severe acute respiratory syndrome coronavirus 2. "Yet, soluble CD59 has not been previously considered as either a chronic low-grade inflammation or an ageing marker, although CD59-mediated protection from membrane attack complex formation curbed COVID-19 progression." (PMID 39518935, 2024). "The previous study has found higher CD46, CD55, and CD59 levels in monocytes of COVID-19 patients than in healthy people, especially CD55 levels correlated with plasma inflammatory markers such as CRP and serum amyloid A during acute infection." (PMID 36820087, 2023). "None of these markers, however, was associated with disease severity, since similar surface expression of mC1q, mC3, CD55 and CD59 was observed when COVID-19 patients were grouped in mild-moderate versus severe disease." (PMID 35250994, 2022). "Interestingly, expression of both CD55 and CD59 membrane-bound complement inhibitors was found specifically elevated in intermediate CD14highCD16+ monocytes from COVID-19 patients when compared to HCs (respectively)." (PMID 35250994, 2022). "A study of transcriptional profiling indicated that the complement gene of CD59 glycoprotein down-regulated in COVID-19 patients, compared with negative controls." (PMID 36091008, 2022). "Greater cellular expression and/or deposition of complement markers on monocytes occurs in acute COVID-19 and is associated with a concomitant rise in CD55 but not CD59 expression." (PMID 35250994, 2022). "Interestingly, we found elevated CD55 but not CD59 monocyte surface expression levels in COVID-19 patients when compared to the control group, consistent with a compensatory mechanism in the setting of persistent complement activation." (PMID 35250994, 2022). "CD55 and CD59, but not CD46, are involved in the hyperactivation and deposition of the complement factors C3, C3b/iC3b/C3d and C5b-9 in infected lung lesions of coronavirus disease 2019 (COVID-19)-affected people." (PMID 39599800, 2024).
multiple myeloma (6 papers, 2013 to 2024). "PIGM expression as validated on protein level using Western blotting, flow cytometry and immunohistochemistry is associated with CD55/CD59 expression on myeloma cell lines and thus impacts on cell surface expressed GPI-anchored receptors." (PMID 24386263, 2013). "One study already demonstrated a role for CD46 and CD59 upregulation in human multiple myeloma, which limits the efficacy of immunotherapy by isatuximab." (PMID 39599800, 2024). "In contrast, therapeutic suppression of CD46 expression and inhibition of CD59 by specific peptides render multiple myeloma treatment with daratumumab and isatuximab far more effective." (PMID 39599800, 2024). "First, an increase in the expression of CIPs, including CD55 and CD59, protects myeloma cells from complement attack via CDC, leading to refractoriness to mAb." (PMID 38284882, 2024). "The functional role of these membrane proteins in myeloma biology ranges from cell adhesion, immune escape (complement inhibition, CD59) to modification of cell signaling (glypicans)." (PMID 24386263, 2013). "To further explore the mechanisms that contribute to the refractoriness of myeloma cells toward CD26mAb therapy, we assessed the levels of complement inhibitory proteins (CIP) CD55 and CD59 in myeloma cells incubated with one of five HDACi for 48 hours." (PMID 38284882, 2024). "The expression of GPI-anchored proteins with known functions in myeloma cells, such as CD55 and CD59 has been demonstrated." (PMID 24386263, 2013). "Furthermore, neutralization of CD59 with the CD59 inhibitor, recombinant ILYd4, sensitized ARH-77 myeloma cells to the CDC effect mediated by rituximab (20 μg/mL) in a dose-dependent manner." (PMID 36359760, 2022). "Resistance to DARA may result from upregulation of the complement inhibitory proteins CD55 and CD59, downregulation of the DARA target CD38 on myeloma cells or altered expression of the checkpoint inhibitor ligand programmed death ligand-1 (PD-L1) or other mechanisms." (PMID 36359760, 2022).